DAXX (death domain associated protein)
Diseases named in the same sentence as DAXX in open-access papers (continued):
Sharing a sentence is not in itself a finding about the gene and the disease.
tumor (123 papers, 2012 to 2026). "In a minority of cases, tumours exhibit loss of DAXX (a binding partner of ATRX) and, more rarely still, ALT-like processes operate in tumours with neither ATRX nor DAXX loss." (PMID 39921567, 2025). "The overexpression of DAXX is a common feature of various cancers, and is associated with tumor occurrence, disease progression." (PMID 39669558, 2024). "In this context, DAXX overexpression is associated with ovarian and prostate carcinogenesis but appears to hold tumor-suppressing properties as well." (PMID 39200236, 2024). "To summarize, an increasing amount of research in numerous types of neoplasia has underlined the implications of DAXX and HJURP in disease pathogenesis and has highlighted clinicopathological and prognostic correlations." (PMID 37958340, 2023). "ATRX (α-thalassemia/mental retardation syndrome X-linked) and its binding partner DAXX (death domain-associated protein 6) are tumor suppressing histone chaperones that promote histone H3.3 deposition and remodeling at telomeric regions." (PMID 37046606, 2023). "Whereas the levels of DAXX expression directly correlate with its ability to promote tumor growth, the molecular mechanisms underlying DAXX’s oncogenic function have begun to emerge." (PMID 37045819, 2023). "The results strongly show that the human genome is crucial to promote tumor growth after the loss of ATRX or DAXX." (PMID 37190157, 2023). "While it has been the subject of a considerable number of studies, no contradictory results have been reported, with researchers agreeing on the overall tumor-promoting role of DAXX loss in pancreas tumorigenesis." (PMID 37958340, 2023). "Whole exome sequencing of non-familial pNETs revealed inactivating-to-missense mutations in either ATRX or DAXX in up to 65% of tumors, predicting tumor suppressive roles in pNET pathogenesis." (PMID 34680266, 2021). "ALT and DAXX/ATRX loss have been correlated with higher tumor stage and grade and are therefore considered a late event in PanNET tumorigenesis." (PMID 30657883, 2019). "In predominantly non-metastatic and well-differentiated/intermediate grade PanNETs, however, loss of DAXX/ATRX by IHC correlated with higher tumor grade and stage, risk for metastasis, and worse survival." (PMID 31692857, 2019). "Since then, mutations in both ATRX and DAXX have been found in a variety of different tumor types and seem to be especially prevalent in tumors associated with the central nervous system." (PMID 29479426, 2018). "The loss of DAXX or ATRX correlated with tumor stage and metastasis, reduced time of relapse-free survival and decreased time of tumor-associated survival." (PMID 28591701, 2017). "Our findings suggest that targeting tumours with loss of expression for DAXX and/or ATRX may be of particular interest for treating highly aggressive UC in veterinary oncology." (PMID 41472189, 2025). "Similarly, the loss of ATRX/DAXX immunohistochemical expression was identified in 18/46 cases of PanNET tumors and was correlated with tumor size larger than 5 cm." (PMID 37958340, 2023). "DAXX gene is implicated in malignant transformation and tumor promotion." (PMID 37897503, 2023). "In conclusion, DAXX exerts a tumorigenic role in brain carcinogenesis and constitutes, furthermore, a potential diagnostic biomarker for tumor grade assessment, as well as an indicator of prognosis, specifically in the fields of patients’ OS and expected response to therapy." (PMID 37958340, 2023).
tumor (continued). "A recent large study involving 2500 matched tumor–control samples from 36 different tumor types suggests that whereas the telomere content of tumors with ATRX or DAXX mutations is increased, tumors with TERT modifications show a moderate decrease in telomere content." (PMID 35565379, 2022). "It is conceivable that transfected NT-3 cells develop only a partial ALT phenotype accompanied by a lower responsiveness to Berzozertib compared to DAXX mutated tumor cells, since siRNA-mediated DAXX knockdown resulted in only a partial reduction in DAXX expression." (PMID 36269546, 2022). "The loss-of-function of ATRX and, less frequently, DAXX affects telomeric stability and results in telomerase-independent maintenance through alternative lengthening of telomeres (ALTs) in H3.3G34R/V mutant tumour cells." (PMID 35382567, 2022). "However, the emerging different role of ALT activation and DAXX/ATRX loss in metastasised tumours and in affecting patient overall survival poses some questions for its clinical implication." (PMID 33975869, 2022). "Furthermore, we were able to stain serial tumor specimens with antibodies to DAXX and ATRX, the mutation status of which has been added to the criteria of well-differentiated NETs." (PMID 33108599, 2020). "Additionally, 18 tumor samples had both ATRX/DAXX truncating or other missense mutations and TERT alterations." (PMID 32024817, 2020). "Second, although mutations of DAXX/ATRX critically enhance tumor malignancy, tumor relapse and metastasis formation may also occur in the setting of tumors with an intact DAXX/ATRX machinery, as observed in our study as well as in others." (PMID 31819132, 2019). "Mutations of DAXX were significantly associated with increased tumor size (p = 0.05)." (PMID 31819132, 2019). "DAXX mutations have been identified in a wide range of tumor types, at a rate of 43%." (PMID 31850367, 2019). "Similar to a number of recent studies, we have demonstrated in this cohort of PanNETs that, in additional to pathologic stage and grade of the tumor, mutations in DAXX, ATRX, and MEN1 are associated with adverse clinical outcome in comparison to those without these mutations." (PMID 30315258, 2018). "ATRX or DAXX loss was proved to be an independent predictor for OS of PanNETs in a multivariate Cox regression analysis including well-established risk factors; tumor stage and tumor grade." (PMID 28591701, 2017). "Death-associated protein 6 (DAXX) has been shown to regulate PTX-sensitivity in tumor." (PMID 26900348, 2016). "The suggestion that ATRX/DAXX defects leading to ALT occurs only in a later stage is compatible with the fact that in hereditary-associated tumors there is an anticipation in the manifestation of the neoplasia." (PMID 27411289, 2016). "In total, four out of six patients had mutations in either ATRX or DAXX with subsequent protein loss in the primary tumor (ATRX loss in one case, DAXX loss in three cases)." (PMID 39954168, 2025). "Both tumor suppressor genes, DAXX and ATRX were found to affect 46% of all cases, with a higher prevalence in primary tumors with evidence of metastases." (PMID 41350422, 2025). "Using lentivirus-mediated shRNA knockdown of DAXX in SAS and SCC25 cell lines, the researchers discovered that suppressing DAXX expression significantly reduced cell proliferation and tumour growth both in vitro and in vivo." (PMID 40987316, 2025).
tumor (continued). "DAXX is a multifunctional protein that plays a role in regulating gene expression, DNA repair, cell cycle control, and tumor suppression." (PMID 41357233, 2025). "We detected alterations in DAXX, MEN1, and ATRX, with mutations in the latter being only observed in samples extracted from primary tumor sites; these biomarkers have been shown to have prognostic significance in pancreatic NENs." (PMID 39825572, 2025). "The loss of DAXX and ATRX expression is associated with shorter patient survival and more aggressive tumour behaviour in PanNENs." (PMID 41472189, 2025). "Our present study attempts to shed light on the implication of DAXX, HJURP and CENPA in the carcinogenesis of UMs and associate their immunohistochemical expression in tumor tissues with patients’ clinicopathological parameters and prognosis." (PMID 39200236, 2024). "In contrast to development processes, altered functions of HIRA and DAXX as H3.3 histone chaperones have distinct consequences in tumor development and progression." (PMID 38297159, 2024). "Such neoplasms are also enriched in MEN1 and ATRX/DAXX mutations and can harbor high-TMB as an actionable target." (PMID 39331358, 2024). "Further, our analysis shows that MEN1, DAXX or ATRX and PTEN mutations commonly co-occur, suggesting that combined loss of those tumor suppressors is likely a key event in pancreatic neuroendocrine cell tumorigenesis." (PMID 38609433, 2024). "DAXX depletion attenuates, while its overexpression enhances, lipogenic gene expression, lipogenesis, and tumor growth." (PMID 37045819, 2023). "A critical insight into the tumor suppressor mechanisms of DAXX and ATRX comes from the mutual exclusivity of mutations, suggesting their shared function in tumor suppression." (PMID 37633949, 2023). "Of note, the expression of DAXX and HJURP has been associated with a multitude of clinicopathological parameters, including disease stage, tumor grade, patients’ overall and disease-free survival, as well as lymphovascular invasion." (PMID 37958340, 2023). "To conclude, DAXX has been reported as exerting both tumor-promoting and tumor-suppressing properties in CRC, while HJURP appears to play a protective role and was correlated with longer OS." (PMID 37958340, 2023). "Extensive research has emphasized the role of DAXX and HJURP, among other biomolecules implicated in epigenetic mechanisms, in the pathogenesis of a great variety of neoplasms." (PMID 37958340, 2023). "The group of Amanda R. Wasylishen used genetically engineered mouse models combined with environmental stress to evaluate the tumor suppressor functions of DAXX and ATRX in the mouse pancreas." (PMID 37190157, 2023). "The wild-type DAXX/ATRX complex regulates chromatin remodeling; however, the impact of DAXX/ATRX loss on tumor progression is poorly understood." (PMID 37190177, 2023). "As pNENs were the most analyzed tumor in GEP-NEN (epi)genomics, and the genes MEN1, DAXX, and ATRX are the most frequently mutated in pNENs, we investigated their mutational status across racial groups via IHC analyses." (PMID 36969744, 2022). "DAXX and ATRX function as tumor suppressors that are frequently mutated in ALT cancers, yet their precise role in regulating ALT is not fully elucidated." (PMID 36028493, 2022). "ATRX/DAXX loss/mutations and ALT positivity are associated with a more aggressive phenotype, such as a larger tumor size, high grade, advanced stage, chromosomal instability, metastatic disease, and poor survival." (PMID 36556070, 2022). "ATRX together with DAXX encode a complex that deposits the histone variant H3.3 into repetitive heterochromatin, including retrotransposons, pericentric heterochromatin, and telomeres, the latter of which show deregulation in ATRX/DAXX-mutant tumours." (PMID 35975235, 2022).
tumor (continued). "The differences in levels of seven EMT-associated markers, Ki-67, DAXX, CD24, CD44, vimentin, laminin and PDX1 plus CgA and NSE (neuroendocrine markers) enabled a distinct molecular signature for each tumour grade to be generated." (PMID 36362433, 2022). "The chromatin factor alpha-thalassemia/mental retardation X-linked chromatin remodeler (ATRX), death domain-associated protein (DAXX), and H3.3 undergo high-frequency mutations in ALT+ tumor cells." (PMID 35565323, 2022). "CD24, CD44, laminin, CD49, CDX2, CK6 and DAXX had lower expression in the tumour relative to that in the non-tumour tissue." (PMID 36362433, 2022). "In PanNETs, there is a high ratio of inactivated to missense mutations in DAXX/ATRX, suggesting that they function as tumor suppressor genes." (PMID 35087762, 2021). "Human tumor studies have highlighted the pathological and prognostic significance of ATRX/DAXX mutations." (PMID 34680266, 2021). "Tumours in subgroup T2 harboured more mutations in ATRX, DAXX and MEN1 with recurrent loss/LOH across 11 chromosomes." (PMID 33536587, 2021). "PDX1 presented hypermethylation and lower expression in tumours with mutations in the ATRX/DAXX/MEN1 genes (T2 and T3) than in wild-type tumours (T1)." (PMID 33536587, 2021). "DAXX has been reported to have a tumor-promoting effect in vitro and in vivo in experimental models of OC, with increase in proliferation, survival, colony formation, and migration." (PMID 32533344, 2020). "Using a xenograft mouse model, we demonstrated that the MKN45 cells formed smaller tumours when DAXX was overexpressed." (PMID 32203224, 2020). "Of genes previously reported as commonly mutated in PNETs, only PDGFRA and MTOR were found to be mutated in a few tumor samples, and other genes, including ATM, ATRX, TSC2, DAXX, VHL, and MEN1, were mutated only in individual samples." (PMID 32586046, 2020). "DAXX depletion significantly increased the tumor growth rate and resulted in 100% of mice developing tumors." (PMID 32864429, 2020). "In this study, we found that total DAXX expression was higher in tumor tissues from the TCGA dataset than in normal tissues." (PMID 32641734, 2020). "In conclusion, the present study is the first to document a potential role for DAXX in mediating tumor progression and affecting outcome in metastatic HGSC, whereas ATRX expression does not appear to be informative in this tumor." (PMID 32533344, 2020). "DAXX overexpression significantly inhibited tumour growth as documented by the decrease in tumour size and weight." (PMID 32203224, 2020). "We screened MEN1, DAXX and ATRX genes for mutations and we classified DAXX/ATRX mutated samples, those tumours which are mutated in either or both the genes." (PMID 33288854, 2020). "ATRX/DAXX loss occurs in 18 and 25% of PanNETs and leads to ALT phenomenon, chromosomal instability and higher tumor stage suggesting this mutation is a late event in the neoplastic transformation." (PMID 32537434, 2020). "DAXX depletion resulted in 100% of mice developing slightly larger tumors, suggesting that E2-inducd DAXX expression inhibits TICs and tumor initiation." (PMID 32864429, 2020). "DAXX expression had little effect on quercetin-treated mice in regards to tumor growth rate or percenatge of mice developing tumors." (PMID 32864429, 2020). "DAXX and DISC1 have been associated with tumor invasion in previous studies; to our knowledge, DRD3 has not." (PMID 31850367, 2019). "The present review focuses on novel and alternative therapeutic options for treating GBM by inducing tumor senescence and apoptosis through the mechanisms of telomerase and ATRX/death-domain associated protein (DAXX)." (PMID 30625996, 2019).
tumor (continued). "Biologically, more recent studies have provided compelling evidence that DAXX can function as a tumor suppressor or an oncogene." (PMID 31350900, 2019). "Taken together, our findings suggest that mutations of DAXX and ATRX are hallmarks of tumor progression, and that they can occur rarely in panNETs ≤2 cm with pathologically-evident malignant potential." (PMID 31819132, 2019). "From these studies, it is clear that the roles of DAXX and ATRX in cancer are complex and dependent on many factors, including the accompanying mutations, the tumor type, and alterations in histone variant expression." (PMID 29479426, 2018). "The majority of mutations in ATRX, DAXX, and MEN1 were truncation mutations (stopgain or frameshift) and loss of function consistent with their role as tumor suppressors." (PMID 30315258, 2018). "We showed that a tumor-derived DAXX mutation has substantially weakened binding affinity for ATRX, a finding that underscores the likely need for ATRX–DAXX complex formation in suppression of tumorigenesis." (PMID 29084956, 2017). "The most prevalent primary tumor variants were in the MEN1 (42%), DAXX (11%), ATRX (10%), and TSC2 (8%) genes." (PMID 29212165, 2017). "The high frequency of inactivating mutations of DAXX and ATRX genes in human tumors points to tumor suppression activities of this complex." (PMID 29084956, 2017). "Genotyping revealed that the majority of the primary tumor variants were identified in MEN1 (42.2%), DAXX (11.1%), ATRX (10%), and TSC2 (7.8%) genes." (PMID 29212165, 2017). "Exome data also revealed one nonsense mutation in death-domain associated protein (DAXX), another gene previously associated with ALT, and the tumor showed ALT positivity." (PMID 26891131, 2016). "Through its ability to repress tumor suppressors, DAXX would be expected to induce tumor growth or survival." (PMID 26097870, 2015). "The difference in DNA methylation between RFS and n/RFS primary tumours was less considerable, although a statistically significant difference was observed for DAXX, P<0.0001; RXRA, P<0.01; C8orf46, P=0.01; NCOR2 and MSI2 (P<0.05; t-test) enhancer regions." (PMID 26169690, 2015). "Mutations in members of the ATRX/DAXX chromatin remodeling complex have been implicated in the ALT mechanism, in both ALT-positive cell lines and tumor samples." (PMID 26001292, 2015). "This context dependence underscores that ATRX/DAXX loss is not intrinsically protective or detrimental, but its outcome is shaped by the tumor’s replication dynamics and genomic environment." (PMID 41148828, 2025). "In contrast, cytoplasmic localisation of DAXX has been observed in certain human tumour types, for example, in gastric cancer, and may carry additional biological significance." (PMID 41472189, 2025). "Mutations of DAXX and ATRX appeared to correlate with loss of nuclear immunolabelling, as seen in PanNENs, although exceptions may occur depending on the tumour type." (PMID 41472189, 2025). "Thus, the most commonly mutated genes in sporadic GEP‐NETs are MEN1, death‐domain‐associated protein (DAXX), and ATRX Chromatin Remodeler (ATRX), occurring in 40%, 25%, and 17% of tumours, respectively." (PMID 39579056, 2025). "Overall, DAXX upregulation is designated as a tumor-promoting factor in ESCCs and could be utilized in the fields of disease staging, tumor grading, and assessment of OS." (PMID 37958340, 2023). "Among them, death domain-associated protein (DAXX) and Holliday junction recognition protein (HJURP) are two of the most extensively studied biomolecules due to their central contribution in a variety of epigenetic modifications implicated in neoplasia." (PMID 37958340, 2023). "DAXX and HJURP are implicated in a multitude of cellular processes, including telomere lengthening, cell apoptosis, chromosome stability, and regulation of various oncogenes’ expression, all of which play key roles both in tumorigenesis and tumor suppression." (PMID 37958340, 2023).